ENTPD3 (ectonucleoside triphosphate diphosphohydrolase 3)
Description:
Catalyzes the hydrolysis of nucleoside triphosphates (NTPs) and diphosphates (NDPs). The enzyme sequentially removes phosphate groups in two successive steps, converting NTPs to nucleoside monophosphates (NMPs) via NDP intermediates. This activity contributes to the regulation of extracellular levels of nucleotides. Has a preference for the hydrolysis of ATP. Does not hydrolyzes AMP.
Synonyms: CD39L3; NTPDase-3; HB6
Tractability: Antibody: its Gene Ontology location is reachable by antibodies, with high confidence; UniProt places it where antibodies can reach, with medium confidence; UniProt predicts a signal peptide or a membrane-spanning region. PROTAC: a small molecule that binds it is known.
Target class: Enzyme; Hydrolase
Gene: Protein-coding gene on chromosome 3 (40,387,184 to 40,428,744, forward strand). Ensembl gene ENSG00000168032.
Subcellular location: Cell membrane
Subcellular location (Human Protein Atlas): Cytosol
Pathways (Reactome):
Metabolism: Phosphate bond hydrolysis by NTPDase proteins
Gene Ontology:
Molecular function: ADP phosphatase activity; apyrase activity; ATP hydrolysis activity; CDP phosphatase activity; CTPase activity; GDP phosphatase activity; GTPase activity; IDP phosphatase activity; ITPase activity; nucleoside diphosphate phosphatase activity; protein binding; ribonucleoside triphosphate phosphatase activity; UDP phosphatase activity; hydrolase activity; pyrophosphatase activity
Biological process: ribonucleoside diphosphate catabolic process; ribonucleoside triphosphate catabolic process; nucleoside diphosphate catabolic process
Cellular component: plasma membrane
Genetic constraint (gnomAD): Loss-of-function variants: 61 observed, 51.91 expected, observed/expected ratio (o/e) 1.17, 90% interval 0.95 to 1.45. The upper end of that interval is the gene's LOEUF score, 1.45, which puts it in group 6 of 6, group 1 being the genes least tolerant of losing a copy. Missense variants: 581 observed, 662.1 expected, observed/expected ratio (o/e) 0.88, 90% interval 0.82 to 0.94. Synonymous variants: 218 observed, 250.08 expected, observed/expected ratio (o/e) 0.87, 90% interval 0.78 to 0.98.
Homologues: Orthologues: chimpanzee ENTPD3 (99% identical), macaque ENTPD3 (98% identical), dog ENTPD3 (83% identical), rabbit ENTPD3 (83% identical), mouse Entpd3 (81% identical), rat Entpd3 (80% identical), pig ENTPD3 (79% identical), guinea pig ENTPD3 (74% identical), tropical clawed frog entpd3 (59% identical), zebrafish entpd3 (47% identical). Paralogues in human: ENTPD2 (38% identical), ENTPD8 (36% identical), ENTPD1 (34% identical), ENTPD4 (25% identical), ENTPD7 (24% identical), ENTPD5 (21% identical), ENTPD6 (19% identical).
Diseases named in the same sentence as ENTPD3 in open-access papers:
ENTPD3 is named in the same sentence as 33 diseases in open-access papers, as found by Europe PMC text mining. Sharing a sentence is not in itself a finding about the gene and the disease. The quoted sentences say what the papers report.
breast carcinoma (6 papers, 2019 to 2025). "In this study, by reducing the hydrolase activity of ENTPD3 through site-directed mutagenesis and observing the effect of the mutated ENTPD3 on cell processes at cellular and animal levels, we proved that ENTPD3 also inhibited the progression of breast cancer by degrading eATP." (PMID 31754326, 2019). "Overexpression of ENTPD3 in breast cancer cell lines inhibited EMT through regulating eATP, and abnormal regulation of EMT in endometrial epithelial cells was closely associated with impaired endometrial receptivity." (PMID 39872439, 2024). "The present study showed that GATA3 blocked breast cancer cell motility by up-regulating ENTPD3 expression, which in turn hydrolyzed eATP in the tumor microenvironment." (PMID 31754326, 2019). "Previous studies revealed that EMT was calcium signaling-dependent and eATP stimulated calcium ion influx 18, 23 Thus, the finding on the hydrolysis of eATP by ENTPD3 indicates that ENTPD3 restrains EMT by hydrolyzing eATP in human breast cancer." (PMID 31754326, 2019). "The ENTPD3-mediated hydrolysis of eATP in the cancer microenvironment suppressed breast cancer cell dissemination and served as a tumor suppressor." (PMID 31754326, 2019). "Specifically, GATA3 accelerated the hydrolysis of eATP and suppressed breast cancer cell metastasis by up-regulating ENTPD3." (PMID 31754326, 2019). "IHC revealed that ENTPD3 was localized to breast cancer cell membranes and the cytoplasm, and showed a positive correlation with ERα." (PMID 31754326, 2019). "Taken together, our findings support the notion that ENTPD3 is a tumor suppressor in breast cancers." (PMID 31754326, 2019). "We found that ENTPD3 was a favorable prognostic factor in patients with breast cancer, either RFS or OS." (PMID 31754326, 2019). "In the GOBO database, the ENTPD3 mRNA level was positively correlated to estrogen receptor α (ERα) and negatively correlated to tumor histopathological grade in patients with breast cancer." (PMID 31754326, 2019). "Here, we demonstrate that GATA3 reduces the ATP level in the breast cancer microenvironment and inhibits breast cancer metastasis by up-regulating ectonucleoside triphosphate diphosphohydrolase 3 (ENTPD3)." (PMID 31754326, 2019). "We demonstrated that ENTPD3 suppressed the expression of vimentin and promoted the expression of E-cadherin, suggesting that ENTPD3 inhibited breast cancer EMT." (PMID 31754326, 2019). "In recent years, the role of ENTPD3 in glucose homeostasis and cancer progression has also been preliminarily explored, identifying it as a marker for human mature pancreatic β-cells and a tumor suppressor in breast cancer." (PMID 38927096, 2024). "A recent study by Li and colleagues identified that GATA3 could reduce extracellular ATP (eATP) in the breast cancer microenvironment by upregulating ectonucleoside triphosphate diphosphohydrolase 3 (ENTPD3), an eATP hydrolytic enzyme." (PMID 33298139, 2020). "In addition, ENTPD3 expression in the luminal A subtype was highest among all breast cancer molecular subtypes." (PMID 31754326, 2019). "We found that ENTPD3 inhibited the metastasis of breast cancer." (PMID 31754326, 2019). "By analyzing the functions of 20 genes with the greatest variation in differential expression, we discovered that ENTPD3 may be a key downstream molecular regulator of GATA3 that inhibits breast cancer metastases." (PMID 31754326, 2019). "Finally, we confirmed that the expression of ENTPD3 was a favorable biomarker of prognosis in a large sample of patients with breast cancer." (PMID 31754326, 2019). "Therefore, this study clarifies that ENTPD3 inhibits the metastasis and progression of breast cancer." (PMID 31754326, 2019). "ENTPD3 hydrolyzes ATP in tumor microenvironment and suppresses breast cancer metastasis." (PMID 31754326, 2019). "In the future, a combination of traditional chemotherapy with strategies to augment ENTPD3 could be a potential strategy to improve breast cancer treatment." (PMID 31754326, 2019).
breast carcinoma (continued). "Also, we showed that GATA3 and ENTPD3 were co-expressed in breast cancer at the protein level." (PMID 31754326, 2019). "Luminal cells subset 2 consisted of cells expressing genes ENTPD3, SRRM3, and GPM6A (corresponding to breast cancer-related genes)." (PMID 40573402, 2025). "In the present study, we demonstrated that ENTPD3 is a novel downstream effector of GATA3 and acts as a tumor suppressor in human breast cancer by hydrolyzing eATP." (PMID 31754326, 2019). "Our study has identified a novel effector of GATA3, ENTPD3, and provides a distinct perspective on the mechanism involved the GATA3 suppression of breast cancer progression and metastases." (PMID 31754326, 2019). "Dual-luciferase reporter assays demonstrated that GATA3 boosted the activity of the ENTPD3-promoter reporter and that deleting the GATA3-binding site diminished GATA3-mediated activity in MDA-MB-231 breast cancer cells." (PMID 31754326, 2019). "To test whether the inhibition of tumors is mediated by the activity of the ENTPD3's ATPase, we used the same method to eliminate or weaken the enzymatic activity of ENTPD3 in MDA-MB-231 breast cancer cells." (PMID 31754326, 2019). "Thus, the up-regulation of ENTPD3-mediated GATA3 not only inhibits breast cancer cell motility, but also modulates the tumor microenvironment to repress breast cancer cell metastasis." (PMID 31754326, 2019). "ENTPD3 was expressed in MCF-7 breast cancer cells with lower motility, but absent in MDA-MB-231 cells." (PMID 31754326, 2019).
Parkinson disease (3 papers, 2019 to 2024). A progressive degenerative disorder of the central nervous system characterized by loss of dopamine producing neurons in the substantia nigra and the presence of Lewy bodies in the substantia nigra and locus coeruleus. "ENTPD3 has been reported to be associated with various diseases, including cancers and Parkinson’s disease." (PMID 39872439, 2024). "Previous studies have well characterized the dysfunction of ENTPD3 in human Parkinson’s disease, Alzheimer’s disease, and Crohn’s disease." (PMID 38927096, 2024). "Previous studies have described the aberrant function of ENTPD3 in human Crohn's, Parkinson's, and Alzheimer's diseases 43-45." (PMID 31754326, 2019).
bladder cancer (2 papers, 2019). "In a mouse model of bladder cancer, the expression of ENTPD3 gradually decreased during cancer progression." (PMID 31754326, 2019). "In human bladder cancer cell lines, the expression of ENTPD3 was present in RT4 cells having a low histological grade, but was absent in T24 cells with a high histological grade 46." (PMID 31754326, 2019). "This suggests that the absence of ENTPD3 expression is a marker of the malignant transformation in human bladder cancer cells." (PMID 31754326, 2019).
gastric cancer (2 papers, 2023 to 2024). A primary or metastatic malignant neoplasm involving the stomach. "As would be expected, high EVPL expression implied a suboptimal response to nivolumab and pembrolizumab in melanoma, while gastric cancer patients with high ENTPD3 expression responded visibly better to pembrolizumab." (PMID 38927096, 2024). "When the eight characteristic genes (ENTPD3, PDZD4, CNN1, GTPBP4, FPGS, UTP25, CENPW, and FAM111A) are all fitted into one variable, the AUC of the ROC curve is 0.996, indicating a good diagnostic efficiency for gastric cancer." (PMID 37007099, 2023). "We have established the early diagnosis model of eight characteristic genes (ENTPD3, PDZD4, CNN1, GTPBP4, FPGS, UTP25, CENPW, and FAM111A) for gastric cancer." (PMID 37007099, 2023).
adenoma (1 paper, 2024). A neoplasm arising from the epithelium. "We noted that EVPL and ENTPD3 were already abnormally expressed at the adenoma stage compared to normal colorectal mucosa, and when colorectal adenoma progressed to colorectal adenocarcinoma, ENTPD3 expression was further downregulated." (PMID 38927096, 2024).
brain tumor (1 paper, 2019). "This indicates that, even from a different persepective, the role of the gene ENTPD3 in the development of a brain tumor." (PMID 31208363, 2019).
clear-cell renal cell carcinoma (1 paper, 2024). "We further found that urothelial cancer with high EVPL expression presented as an immune-excluded or immune-desert phenotype, while clear-cell renal cell carcinoma with high ENTPD3 expression leaned to be immune-inflamed." (PMID 38927096, 2024).
colon cancer (1 paper, 2024). "Among the extracellular ENTPDases (CD39, ENTPD2, ENTPD3 and ENTPD8), ENTPD2 had the highest expression in colon tumor tissues, according to analysis of data in GEPIA2." (PMID 38755598, 2024). "Our analysis of CD39, ENTPD3 and ENTPD8 expression in colon cancer cell-derived exosomes revealed relatively low expression in both cell lysates and control cell-derived exosomes (ExoRKO−shNC and ExoDLD1−shNC)." (PMID 38755598, 2024). "In this study, for the first time, we performed a screen and demonstrated that ENTPD2 but not other ATPases (CD39, ENTPD3 and ENTPD8) is highly expressed in human colon cancer cells and is closely associated with poor patient prognosis." (PMID 38755598, 2024). "Here, we found for the first time that ENTPD2 is ubiquitously expressed in colon cancer cells, unlike other ATPases (CD39, ENTPD3 and ENTPD8)." (PMID 38755598, 2024).
metastatic disease (1 paper, 2019). "Furthermore, ENTPD3 inhibits epithelial-to-mesenchymal transition, a key program responsible for the development of metastatic disease." (PMID 31754326, 2019).
Obesity (1 paper, 2022). Accumulation of substantial excess body fat. "Entpd3−/− mice are resistant to high fat diet-induced obesity and have elevated basal metabolic rates, when fed a high fat diet associated with improved glucose tolerance." (PMID 35360246, 2022). "Studies on Entpd3flox/flox;InsCre mice show a similar phenotype indicating Entpd3 in β cells is not protective against diet-induced obesity and insulin resistance." (PMID 35360246, 2022).
schizophrenia (1 paper, 2024). A major psychotic disorder characterized by abnormalities in the perception or expression of reality. "In the comparison including all schizophrenia and control subjects, the mRNA expression levels of ENT1, ENT2, ENTPD1, ENTPD3, and NT5E were not significantly different between the two sexes." (PMID 39404420, 2024). "In an enriched population of ACC pyramidal neurons, the mRNA expression levels of ADK, ENT1, ENT2, ENTPD1, ENTPD3, and NT5E were assessed between individuals with schizophrenia and sex- and age-matched non-psychiatrically ill control subjects." (PMID 39404420, 2024). "In the present study, we assayed the transcript expressions of ADK, ENT1, ENT2, ENTPD1, ENTPD3, and NT5E in an enriched population of pyramidal neurons in the postmortem ACC tissue of patients diagnosed with schizophrenia compared with non-psychiatrically ill sex- and age-matched patients." (PMID 39404420, 2024).
cancer (6 papers, 2019 to 2024). A tumor composed of atypical neoplastic, often pleomorphic cells that invade other tissues. "Due to the dearth of sufficient available data on CRC immunotherapy, we first investigated the ability of EVPL and ENTPD3 expression to predict immunotherapy response in other cancer types." (PMID 38927096, 2024). "An enhanced ENTPD3 level can hydrolyze eATP and inhibit cancer cell metastasis in those patients with lower ENTPD3 expression." (PMID 31754326, 2019). "GATA3 improves the anti-cancer ability of T lymphocytes in the tumor microenvironment by the ENTPD3-catalyzed hydrolysis of eATP." (PMID 31754326, 2019). "Analysis of multiple other cancers further showed that both high EVPL and low ENTPD3 expression predicts poor response to immunotherapy, confirming the tissue-wide and disease-wide applicability of EVPL- and ENTPD3-associated immune dysregulation." (PMID 38927096, 2024). "For cancer patients who have received immune checkpoint inhibitor (ICI) therapies, both low EVPL and high ENTPD3 expression indicated a longer post-immunotherapy survival." (PMID 38927096, 2024). "However, the significance of ENTPD3 in human cancers remains unclear." (PMID 31754326, 2019). "Single-cell analysis highlighted a cancer-associated fibroblast (CAF) subset that specifically expressed ENTPD3 in CRC, which exhibited high heterogeneity and unique tumor-suppressive features that were completely different from classical cancer-promoting CAFs." (PMID 38927096, 2024). "However, the role of ENTPD3 has not yet been well defined in human cancers." (PMID 31754326, 2019).
tumor (4 papers, 2019 to 2024). "Molecular markers and enrichment analysis proved the great heterogeneity within the CAF population in CRC and indicated the potential anti-tumor functions of ENTPD3+ CAFs distinct from prototypical tumor-promoting-like CAFs." (PMID 38927096, 2024). "The low ENTPD3 expression group showed a completely homogeneous immune landscape with considerably high tumor purity and low infiltration of stromal cells and immune cells." (PMID 38927096, 2024). "For the 5 patients who underwent pre-treatment tumor biopsies, ENTPD3 was observed to be expressed in small amounts in epithelial cells." (PMID 38927096, 2024). "For the 5 patients who only underwent post-treatment tumor biopsies, ENTPD3+ CAFs were also obviously present in 3 pCR patients (P15, P17, P29) but completely absent in 2 non-pCR patients (P12, P18)." (PMID 38927096, 2024). "Significantly, tumors grew in the lungs or buttocks of all control or mutation M224 group mice; however, three mice in ENTPD3 groups showed no tumor formation." (PMID 31754326, 2019). "Digging deeper into the role of the T2DM and CRC core gene ENTPD3 in CRC anti-tumor immunity would be instrumental in optimizing the clinical values of ICIs in the era of immunotherapy, whether in terms of predictive biomarkers or improving immunotherapy efficiency." (PMID 38927096, 2024). "From a perspective beyond traditional biomarkers, the presence status of ENTPD3+ CAFs in CRC patients was likely a natural mapping of the balance between the body’s anti-tumor immune system and the constantly changing tumor immune microenvironment." (PMID 38927096, 2024). "In the present study, we verify that ENTPD3 is a novel downstream target of GATA3 and is essential for its role as a tumor suppressor." (PMID 31754326, 2019). "Pseudotime analysis showed that ENTPD3+ CAFs were at the ultimate terminal phase of differentiation among all CAF subsets, prompting that their emergence may signify reactive anti-tumor immunity." (PMID 38927096, 2024). "Furthermore, wild-type ENTPD3 suppressed tumor growth in the buttocks of mice that did not grow tumors in their lungs." (PMID 31754326, 2019). "Furthermore, we used the ESTIMATE algorithm to calculate the StromalScore, ImmuneScore, ESTIMATEScore, and tumor purity of CRC samples in the TCGA-CRC cohort and compared the differences in these ESTIMATE scores between the high and low expression groups of EVPL and ENTPD3." (PMID 38927096, 2024).
infection (2 papers, 2022 to 2023). The state of being infected such as from the introduction of a foreign agent such as serum, vaccine, antigenic substance or organism. "In addition, genes related to glycerolipid metabolism (Plpp2), glycolysis metabolism (Pfkp), adipocyte differentiation (Rapgef4), nucleotide metabolism (Entpd3), serine catabolism (Shmt1), retinol metabolism (Akr1b10), and lipid-grading metabolism (Pla2g4f) were upregulated after EgPSC infection." (PMID 36713407, 2022).
ENTPD3 also shares sentences with these, for which no sentence is quoted: Alzheimer disease (2 papers); Crohn disease (2); diabetics (2); angiosarcoma (1); colitis (1); colorectal adenocarcinoma (1); colorectal adenoma (1); endometriosis (1); Ileitis (1); Impaired glucose tolerance (1); Insulin resistance (1); melanoma (1); narcolepsy (1); osteogenesis imperfecta (1); osteoporosis (1); Pain (1); Parkinson's (1); rheumatoid arthritis (1); type 2 diabetes mellitus (1).